FOXN3 (forkhead box N3)
Description:
Acts as a transcriptional repressor. May be involved in DNA damage-inducible cell cycle arrests (checkpoints).
Synonyms: C14orf116; CHES1; PRO1635
Tractability: PROTAC: ubiquitination databases record sites on it.
Gene: Protein-coding gene on chromosome 14 (89,124,871 to 89,619,271, reverse strand). Ensembl gene ENSG00000053254.
Subcellular location: Nucleus
Subcellular location (Human Protein Atlas): Nucleoplasm; Cytosol
Gene Ontology:
Molecular function: protein binding; cis-regulatory region sequence-specific DNA binding; DNA-binding transcription factor activity; DNA-binding transcription factor activity, RNA polymerase II-specific; sequence-specific DNA binding
Biological process: mitotic G2 DNA damage checkpoint signaling; negative regulation of DNA-templated transcription; regulation of DNA-templated transcription; regulation of transcription by RNA polymerase II
Cellular component: chromatin; nucleus
Genetic constraint (gnomAD): Loss-of-function variants: 7 observed, 35.2 expected, observed/expected ratio (o/e) 0.2, 90% interval 0.11 to 0.37. The upper end of that interval is the gene's LOEUF score, 0.37, which puts it in group 1 of 6, group 1 being the genes least tolerant of losing a copy. Missense variants: 451 observed, 613.57 expected, observed/expected ratio (o/e) 0.74, 90% interval 0.68 to 0.8. Synonymous variants: 227 observed, 242.04 expected, observed/expected ratio (o/e) 0.94, 90% interval 0.84 to 1.05.
Homologues: Orthologues: chimpanzee FOXN3 (99% identical), macaque FOXN3 (99% identical), guinea pig FOXN3 (95% identical), pig FOXN3 (94% identical), mouse Foxn3 (93% identical), rabbit FOXN3 (93% identical), rat Foxn3 (93% identical), tropical clawed frog foxn3 (81% identical), zebrafish ches1 (48% identical). Paralogues in human: FOXN2 (43% identical), FOXN4 (23% identical).
Diseases named in the same sentence as FOXN3 in open-access papers:
FOXN3 is named in the same sentence as 69 diseases in open-access papers, as found by Europe PMC text mining. Sharing a sentence is not in itself a finding about the gene and the disease. The quoted sentences say what the papers report.
breast carcinoma (13 papers, 2018 to 2023). "In their study regarding breast cancer, Li and collaborators evaluated the pathophysiological function and underlying mechanism of FOXN3, a forkhead transcriptional repressor that is physically associated with the SIN3a complex in ER+ breast cancer cells." (PMID 38275371, 2023). "The top autosomal DNAm sites were mapped to genes that have been associated with breast cancer and other malignancies (e.g., cg02325951 on FOXN3, cg20262915 and cg19765154 on NAB1, and cg07850329 on BAG1), as well as childhood neurodegeneration (e.g., cg12607525 on UBTF)." (PMID 36966332, 2023). "Here we describe current state of knowledge of FOXN3 functions, and focus on its roles (known and potential) in breast cancer." (PMID 31214487, 2019). "While the roles of FOXN3 role in some cancers have been explored, its role in breast cancer remains unclear." (PMID 31214487, 2019). "Besides, interaction of FOXN3 with NEAT1/SIN3A showed to repress GATA3 in breast cancer metastasis." (PMID 30894512, 2019). "Overexpression of both FOXN3 and NEAT1 in breast cancer led to GATA3 expression impairment and strongly correlated with poor prognosis." (PMID 31003545, 2019). "After inoculating the engineered MCF-7 breast cancer cells into the left abdominal mammary fat pad, it was found that overexpression of either NEAT1 or FOXN3 efficiently promoted lung metastasis in animal models." (PMID 31214490, 2019). "At the same time, NEAT1, which is induced by estrogen in breast cancer, can form FOXN3-NEAT1-SIN3A inhibitory factor, through the interaction with FOXN3 and SIN3A protein complex, and promote epithelial-mesenchymal transformation (EMT) and metastasis, diffusion and invasion of breast cancer cells." (PMID 34804040, 2021). "The other member of FOX protein family, FOXA135, FOXO3a36, and FOXK237,38, can modulate the activity of nuclear receptors via proteins physical interaction; here we speculated that CHES1, also known as FOXN3, may regulate ERα activity through the interaction with ERα in breast cancer cells." (PMID 29752474, 2018).
lung carcinoma (6 papers, 2012 to 2023). "FOXN3 is a direct target of and is downregulated by miR-574-5p to promote the progression of human lung cancer." (PMID 27259277, 2016). "A meta-analysis of the FOXN3 gene (using the oncomine database) demonstrated that among 15 different malignancies (including liver cancer, lung cancer, colon cancer, prostate cancer, laryngeal cancer, glioblastoma multiform, and lymphoma) there was a very marked down-regulation of the FOXN3 gene." (PMID 31214487, 2019). "Forkhead box N3 (FOXN3), an important member of the FOX transcription factor family, is an important tumor suppressor gene that plays a crucial role in several cancers such as liver cancer, lung cancer, and colon cancer." (PMID 37033223, 2023).
melanoma (6 papers, 2019 to 2026). A malignant, usually aggressive tumor composed of atypical, neoplastic melanocytes. "Recent studies have uncovered that FOXN3 functions as a key player in multiple kinds of malignant tumors, such as papillary thyroid cancer, tongue squamous cell carcinoma, melanoma and breast cancer." (PMID 34511432, 2021). "FOXN3 is a tumor suppresser and alterations in FOXN3 are found in of a variety of cancers including melanoma, osteosarcoma, and hepatocellular carcinoma." (PMID 31214487, 2019). "A study in liver and melanoma malignancy cells (where FOXN3 expression has been reported to be decreased compared to corresponding normal tissue) showed that FOXN3 protein can act on the SKIP through its COOH terminal, repressing SKIP mediated TGF-β signaling." (PMID 31214487, 2019). "In summary, our findings provide novel insights into the mechanism of melanoma-derived miR-708-5p in facilitating the formation of an immunosuppressive tumor microenvironment and indicate the potential of miR-708-5p and FOXN3 as therapeutic targets for the treatment of melanoma." (PMID 41872159, 2026).
colon cancer (5 papers, 2018 to 2023). "This study showed that FOXN3 can inhibit the progression of the colon cancer, and that restoration of the function of FOXN3 is expected to become a novel therapeutic strategy for the colon cancer." (PMID 31214487, 2019). "Monitoring revealed that FOXN3 was down-regulated, which promoted the metastasis of the colon cancer cells, and immunohistochemistry showed that knocking out the expression of FOXN3 promotes tumorigenesis of colon cancer cells in the colonic tissues." (PMID 31214487, 2019). "By using such techniques as fluorescence quantitative PCR, Western blot and immunohistochemistry, they found that the mRNA and protein levels of FOXN3 were decreased in the colon cancer tissues." (PMID 31214487, 2019). "Finally, FOXN3 is a protein-coding gene which has a well-known suppressive role in the progression of colon cancer." (PMID 32272578, 2020). "In the subsequently different pretreated colon cancer mouse model experiments, Western blot revealed that FOXN3 was expressed in the normal colon tissues and tumors, demonstrating the reduction in the level of FOXN3 protein." (PMID 31214487, 2019). "Through the GST pull-down assay, they found that FOXN3 and β-catenin could form a complex in the colon cancer cell lines." (PMID 31214487, 2019). "FOXM1 expression has also been associated with resistance to chemotherapy and to ionizing radiation of GBM cells, unlike FOXN3 which inhibited growth, migration and invasion of colon cancer cells and the proliferation of HCC cells." (PMID 30167084, 2018).
hepatocellular carcinoma (5 papers, 2006 to 2020). A malignant tumor that arises from hepatocytes. "Through a blend of primary human hepatocyte, immortalized HepG2 hepatoma cell, and transgenic zebrafish approaches, we found that this SNP increases the expression of the FOXN3 protein and that this transcriptional repressor blunts a glucose utilization transcriptional program in the liver." (PMID 28018294, 2016).
leukemia (5 papers, 2014 to 2022). A malignant (clonal) hematologic disorder, involving hematopoietic stem cells and characterized by the presence of primitive or atypical myeloid or lymphoid cells in the bone marrow and the blood. "We now speculate that FOXN3, as a tumor suppressor gene, is involved in the development of leukemia." (PMID 31214487, 2019). "It is the first time that FOXN3 deletion is observed in leukemia." (PMID 24727659, 2014). "Consistent with our finding, several lines of evidence have recently highlighted the roles of FOXN3, FOXO3, FOXO4, and FOXP3 in leukemia." (PMID 36292640, 2022). "In addition, the mechanisms of the targeted protein of the FOXN3 transcription factor may be discovered through further studies, which will give insight into the novel tumor suppressor gene for the complex network of the development of leukemia." (PMID 31214487, 2019). "Generally speaking, the TS gene regulates proliferation and apoptosis of cells via synergy with other TS genes or oncogenes, indicating that FOXN3 and ZHX1 form a regulatory network in the development of T cells and the genesis of leukemia." (PMID 31214487, 2019).
liver cancer (4 papers, 2019 to 2024). An epithelial or non-epithelial malignant neoplasm that arises from the liver. "In both in vivo and in vitro experiments, FOXN3 can inhibit the proliferation of liver cancer cells significantly." (PMID 31214487, 2019).
acute myeloid leukemia (3 papers, 2019 to 2021). Acute myeloid leukemia (AML) is a group of neoplasms arising from precursor cells committed to the myeloid cell-line differentiation. "He and his research team reported a notable decrease in FOXN3 expression in adult acute myeloid leukemia and their data revealed that FOXN3 exerted tumor-suppressing roles by inhibiting cell proliferation and promoting apoptosis." (PMID 34511432, 2021). "However, the clinical significance of FOXN3 and its potential role in acute myeloid leukaemia (AML) remain largely unknown." (PMID 32078244, 2020).
glioblastoma (3 papers, 2018 to 2021). The most malignant astrocytic tumor (WHO grade IV). "In glioblastoma, low levels of FOXN3 mRNA expression were significantly associated with poor survival of patients not treated with chemotherapy or radiotherapy." (PMID 30167084, 2018). "Although FOXN3 dysregulation has been identified in different types of cancers such as liver and mouth carcinomas, glioblastoma, and Hodgkin's lymphoma, the exact molecular mechanism of its contribution in these cancers needs to be clarified." (PMID 34703931, 2021).
acute leukemia (2 papers, 2014 to 2019). A clonal (malignant) hematopoietic disorder with an acute onset, affecting the bone marrow and the peripheral blood. "We subsequently investigated the expression levels of the FOXN3 in a cohort of acute leukemia samples including 78 AMLs and 19 ALLs." (PMID 24727659, 2014).
colon adenocarcinoma (2 papers, 2019 to 2022). "Given Sun's previous research results, they found when using the oncomine database to analyze the sample datasets in the normal colon tissue and colon adenocarcinoma tissue that compared with the normal tissues, the expression of FOXN3 was decreased in colon adenocarcinoma tissue." (PMID 31214487, 2019).
Hyperglycemia (2 papers, 2019 to 2021). An increased concentration of glucose in the blood. "The blood glucose‐modifying variation within this gene regulates the abundance of both FOXN3 protein and transcript in primary human hepatocytes, with the hyperglycemia risk allele causing increases in both FOXN3 protein and transcript." (PMID 31552709, 2019). "The hyperglycemia risk allele of this variation drives increased expression of liver FOXN3." (PMID 31552709, 2019).
Obesity (2 papers, 2022 to 2025). Accumulation of substantial excess body fat. "Foxn3 is involved in numerous cellular and physiological processes, including cell proliferation, aging, obesity, and cancer." (PMID 39741412, 2025). "The gene to which cg02325951 is annotated, FOXN3, is involved in several physiological processes, such as development, ageing, obesity, and cancer and is expressed in multiple tissues, including the forebrain and midbrain." (PMID 34738878, 2022).
oral cancer (2 papers, 2012 to 2022). "An association between FOXN3 expression and areca nut chewing habits in patients with oral cancer has also been shown." (PMID 35629112, 2022).
oral squamous cell carcinoma (2 papers, 2006 to 2014). "Reduced expression of FOXN3 has been reported in several cancers, such as renal cell carcinoma and oral squamous cell carcinoma." (PMID 24727659, 2014).
papillary thyroid cancer (2 papers, 2021 to 2022). "FOXN3 played a tumor inhibitory role in papillary thyroid carcinoma via inactivating the Wnt/β-catenin pathway." (PMID 35656441, 2022).
alcoholism (1 paper, 2022). "The rs759364 SNP is an intronic variant of FOXN3, which has been associated with alcoholism and cigarette smoking." (PMID 35629112, 2022).
atherosclerosis (1 paper, 2017). A disease characterized by the build-up of fatty material and calcium deposition in the arterial wall resulting in partial or complete occlusion of the arterial lumen. "FOXN3 has also been linked to carotid intima-media thickness (a subclinical measure for atherosclerosis) and plaque in recent fine mapping studies in humans." (PMID 29073909, 2017).
bone fracture (1 paper, 2021). "Moreover, the reported over-expression of FOXN3 during the early stages of MSC osteodifferentiation, and the down-regulation of CD27-AS1 in MSCs of donors with bone fracture, allow us to hypothesise a possible function of Mlinc.128022 in bone remodelling and osteogenesis." (PMID 34088266, 2021).
cervical cancer (1 paper, 2022). A primary or metastatic malignant neoplasm involving the cervix. "In addition, the tumor-promotive role of miR-574-5p has been revealed in other types of cancer, such as cervical cancer and nasopharyngeal carcinoma, respectively targeting QKI and FOXN3, with which interactions were previously discussed in gastric cancer, CRC, and thyroid cancer." (PMID 36671425, 2022).
dengue (1 paper, 2022). "Taken together, these findings suggest that the regulation of TLR9 signaling by miRNA-574-5p and FOXN3 might have an impact on the development of severe dengue and deserves further study to clarify this relationship." (PMID 36251659, 2022).
diabetes (1 paper, 2017). "Another network gene FOXN3 has been associated with fasting blood glucose, serum cholesterol, and diabetes in past GWAS." (PMID 29073909, 2017).
glioma (1 paper, 2021). A benign or malignant brain and spinal cord tumor that arises from glial cells (astrocytes, oligodendrocytes, ependymal cells). "With the purpose of illuminating the potential molecular mechanisms underlying the biological functions of FOXN3 in glioma, further mechanistic studies were performed." (PMID 34511432, 2021). "Taken together, the present study offers novel insights into elucidating biological functions of FOXN3 in glioma." (PMID 34511432, 2021). "This study aimed to evaluate the biological role of forkhead box N3 (FOXN3) in human glioma and clarify the possible molecular mechanisms." (PMID 34511432, 2021). "Taken together, these observations indicate that FOXN3 repressed the expression of malignant phenotype-promoting proteins in glioma cells." (PMID 34511432, 2021). "Herein, it was found that FOXN3 was notably under-expressed in the tumorous tissues and that reduced FOXN3 expression correlated with short overall survival time of patients with glioma." (PMID 34511432, 2021). "Effects of FOXN3 over-expression and depletion on glioma cell proliferation, apoptosis, migration and invasion were assessed by CCK8, colony formation assay, flow cytometry, scratch wound healing assay and Transwell invasion assay, respectively." (PMID 34511432, 2021). "To further characterize the possible role of FOXN3 in human glioma, we performed subsequent cell experiments." (PMID 34511432, 2021). "Herein, FOXN3 protein expression patterns in glioma cell lines (SF126, U87MG, LN229 and U251MG cells) and normal human gliocytes (HEB cells) were assessed via Western blotting." (PMID 34511432, 2021). "In order to explore the role of FOXN3 in human glioma, qPCR analysis was performed to characterize its expression patterns in glioma tissues and healthy brain tissues." (PMID 34511432, 2021). "In consistence with the findings about FOXN3 mRNA expression, Western blotting analysis showed that FOXN3 protein was notably under-expressed in glioma tissues in comparison with normal brain tissues (P < 0.01)." (PMID 34511432, 2021). "The current study aimed to explore potential biological functions of FOXN3 in human glioma and clarify possible molecular mechanism." (PMID 34511432, 2021). "FOXN3 mRNA expression were significantly decreased in the glioma tissues in comparison with normal brain tissues (P < 0.01)." (PMID 34511432, 2021). "In the current study, FOXN3 expression patterns in glioma tissues were characterized via qPCR analysis and Western blotting." (PMID 34511432, 2021). "Gain- and loss-of-function analyses demonstrated that FOXN3 over-expression significantly suppressed proliferation, survival and motility of glioma cells, whereas FOXN3 knockdown remarkably promoted glioma cell proliferation, survival and motility." (PMID 34511432, 2021). "Results showed that FOXN3 was significantly down-regulated in glioma tissues compared with normal tissues." (PMID 34511432, 2021). "Collectively, these results suggest that decreased FOXN3 expression correlates with glioma patients’ poor prognosis." (PMID 34511432, 2021). "Herein, it was found that FOXN3 was markedly under-expressed in glioma tissue samples and glioma cell lines." (PMID 34511432, 2021). "Nevertheless, potential biological functions of FOXN3 in human glioma remain largely unclear." (PMID 34511432, 2021).